NELFA (negative elongation factor complex member A)
Description:
Essential component of the NELF complex, a complex that negatively regulates the elongation of transcription by RNA polymerase II. The NELF complex, which acts via an association with the DSIF complex and causes transcriptional pausing, is counteracted by the P-TEFb kinase complex. (Microbial infection) The NELF complex is involved in HIV-1 latency possibly involving recruitment of PCF11 to paused RNA polymerase II.
Synonyms: NELF-A; WHSC2; P/OKcl.15
Tractability: Small molecule: a structure with a bound ligand is known. PROTAC: ubiquitination databases record sites on it; its protein half-life has been measured.
Gene: Protein-coding gene on chromosome 4 (1,982,717 to 2,041,903, reverse strand). Ensembl gene ENSG00000185049.
Subcellular location: Nucleus
Subcellular location (Human Protein Atlas): Nucleoplasm; Nuclear bodies
Pathways (Reactome):
Disease: Abortive elongation of HIV-1 transcript in the absence of Tat; Formation of HIV elongation complex in the absence of HIV Tat; Formation of HIV-1 elongation complex containing HIV-1 Tat; Formation of the HIV-1 Early Elongation Complex; HIV elongation arrest and recovery; Pausing and recovery of HIV elongation; Pausing and recovery of Tat-mediated HIV elongation; Tat-mediated HIV elongation arrest and recovery; Tat-mediated elongation of the HIV-1 transcript
Gene expression (Transcription): Formation of RNA Pol II elongation complex; Formation of the Early Elongation Complex; RNA Polymerase II Pre-transcription Events; RNA Polymerase II Transcription Elongation
Gene Ontology:
Molecular function: molecular adaptor activity; protein binding; RNA polymerase inhibitor activity; chromatin binding
Biological process: negative regulation of transcription elongation by RNA polymerase II; transcription pausing by RNA polymerase II; positive regulation of transcription by RNA polymerase II
Cellular component: NELF complex; nuclear body; nucleoplasm; nucleus
Genetic constraint (gnomAD): Loss-of-function variants: 33 observed, 46.01 expected, observed/expected ratio (o/e) 0.72, 90% interval 0.54 to 0.96. The synonymous counts are far from expectation, so gnomAD's model fits this gene poorly and the ratio says little. Missense variants: 654 observed, 698.16 expected, observed/expected ratio (o/e) 0.94, 90% interval 0.88 to 1. Synonymous variants: 417 observed, 324.62 expected, observed/expected ratio (o/e) 1.28, 90% interval 1.18 to 1.39.
Homologues: Orthologues: chimpanzee NELFA (100% identical), macaque NELFA (99% identical), dog NELFA (96% identical), mouse Nelfa (96% identical), rat Nelfa (96% identical), pig NELFA (95% identical), guinea pig NELFA (89% identical), tropical clawed frog nelfa (84% identical), zebrafish nelfa (82% identical), Drosophila melanogaster Nelf-A (45% identical).
Diseases named in the same sentence as NELFA in open-access papers:
NELFA is named in the same sentence as 23 diseases in open-access papers, as found by Europe PMC text mining. Sharing a sentence is not in itself a finding about the gene and the disease. The quoted sentences say what the papers report.
microcephaly (6 papers, 2014 to 2021). A congenital or acquired developmental disorder in which the circumference of the head is smaller than normal for the person's age and sex. "We confined the region of susceptibility for microcephaly and seizures to a 330 kb sized region that encompassed seven candidate genes (LETM1, FGFR3, WHSC1, NELFA, C4orf48, NAT8LI, and POLN)." (PMID 29721507, 2018).
breast carcinoma (2 papers, 2023 to 2026). "Loss of NELFA may enhance oncogenic transcriptional programs specifically in TNBC, highlighting its potential relevance as a context-dependent biomarker in aggressive breast cancer subtypes." (PMID 42100387, 2026).
acute myeloid leukemia (1 paper, 2022). Acute myeloid leukemia (AML) is a group of neoplasms arising from precursor cells committed to the myeloid cell-line differentiation. "Interestingly, acute myeloid leukemia (AML) patients with both high NELFA or NELFB expression display low survival rates." (PMID 35409193, 2022).
esophageal squamous cell carcinoma (1 paper, 2020). Esophageal squamous cell carcinoma (ESCC) is a type of esophageal carcinoma (EC) that can affect any part of the esophagus, but is usually located in the upper or middle third. "NELFA mRNA knockdown significantly decreased oesophageal squamous cell carcinoma (ESCC) proliferation and colony formation." (PMID 31845510, 2020).
lymph node metastasis (1 paper, 2020). "The univariate Cox regression analysis confirmed that the NELFA mRNA‐positive rate (P = 0.010), gender (P < 0.001), lymph node metastasis (P < 0.001), T stage (P = 0.009) and TNM stage (P < 0.001) were vital prognostic factors." (PMID 31845510, 2020).
oesophageal cancer (1 paper, 2020). "In our study, the most notable finding was that the noncoding function of NELFA mRNA plays an important role in oesophageal cancer progression." (PMID 31845510, 2020). "Most importantly, we demonstrated that the high expression level of NELFA mRNA was closely related to poor patient survival and might be viewed as an independent prognostic indicator for oesophageal cancer patients." (PMID 31845510, 2020).
periodontitis (1 paper, 2022). An acute or chronic inflammatory process that affects the tissues that surround and support the teeth. "Furthermore, 12 hub genes ranked by the top 10% genes with high degree connectivity and five TFs, including SRF, CNOT4, SIX6, SRRM3, NELFA, and ONECUT3, were identified and might play crucial roles in the molecular pathogenesis of periodontitis." (PMID 35397550, 2022).
cancer (6 papers, 2020 to 2025). A tumor composed of atypical neoplastic, often pleomorphic cells that invade other tissues. "NELFA mRNA was significantly upregulated in ESCC tissues compared with para‐carcinoma tissues (P < 0.001)." (PMID 31845510, 2020). "NELFA mRNA expression was significantly upregulated in ESCC tissues compared with para‐carcinoma tissues." (PMID 31845510, 2020). "In addition, upregulated NELFA mRNA was related to cancer progression and a poor prognosis." (PMID 31845510, 2020).
tumor (5 papers, 2017 to 2025). "The NELFA mRNA‐positive rate was correlated with tumour lymph node metastasis and tumour–node–metastasis (TNM) stage." (PMID 31845510, 2020). "In addition, the NELFA mRNA expression level was positively correlated with tumour lymph node metastasis (P < 0.05) and TNM stage (P < 0.01)." (PMID 31845510, 2020). "Furthermore, through gene expression profiling interactive analysis (GEPIA), we found that the gene expression of USF2 was positively related to RAD17 or NELFA in multiple tumours." (PMID 31845510, 2020).
infection (1 paper, 2020). The state of being infected such as from the introduction of a foreign agent such as serum, vaccine, antigenic substance or organism. "In contrast, in the JiL cell lines, which were generated by isolating clones from the population of cells that were transcriptionally silenced shortly (4 days) after infection, the sgRNAs targeting SUPT5H and NELFA were enriched to a much lesser extent." (PMID 33270809, 2020).
NELFA also shares sentences with these, for which no sentence is quoted: cardiac hypertrophy (15 papers); Wolf-Hirschhorn syndrome (3); colon carcinoma (2); age (1); convulsion (1); glioma (1); heart arrhythmia (1); hypertrophy (1); liver cancer (1); mental retardation (1); Micrognathia (1); Onset (1); triple-negative breast carcinoma (1).